IL6 (interleukin 6)
Diseases named in the same sentence as IL6 in open-access papers (continued):
Sharing a sentence is not in itself a finding about the gene and the disease.
tumor (continued). "Further investigation into CD14+ DC3s revealed that they can originate from CD14− DC2s, driven by tumor-secreted IL-6 and macrophage colony-stimulating factor (M-CSF), hence called tumor-induced CD14+ DC3s." (PMID 40789452, 2025). "Tumor microenvironmental factors such as IL-1β, IL-6, TNF-α, and IFN-γ, promote IMCs accumulation, inhibit their differentiation, and activate their immunosuppressive functions, at which point they are referred to as MDSCs." (PMID 40822347, 2025). "A promoter assay also demonstrated that IL-6 promoter activity was highly enhanced in the group of MSN overexpression compared to the tumor cells with MSN depletion." (PMID 40696387, 2025). "For example, tumor-derived IL-6 and M-CSF convert immature DCs into macrophages and prevent the priming of tumor-specific T cells." (PMID 40165901, 2025). "In the TME, IL‐6/JAK/STAT3 signaling promotes tumor cell proliferation, angiogenesis, and metastasis, while strongly suppressing the antitumor immunity." (PMID 41306557, 2025). "IL-6 is produced by multiple cell types in the tumor microenvironment, including tumor-infiltrating immune cells, stromal cells, and tumor cells themselves." (PMID 40281902, 2025). "Treatment with recombinant IL-6 showed only minimal responses in tumor therapy, accompanied by marked adverse effects." (PMID 40649953, 2025). "Because these have been extensively described for IL-6 pathways, our efforts were mostly focused on the relevant readouts for our proposed model, i.e., cell proliferation, pharmacokinetic parameters, and tumor burden/survival." (PMID 38980514, 2025). "For instance, PTEN loss promotes an inflammatory tumor microenvironment via PI3K/AKT signaling, potentially amplifying the effects of TAM-derived cytokines (e.g., IL-6)." (PMID 41293737, 2025). "Toll-like receptor 5 (TLR-5) signaling and hypoxia within the pre-metastatic niche are responsible for the upregulation of interleukin-6 (IL-6) and tumor-promoting inflammation." (PMID 40002869, 2025). "Tumor cells damage endothelial cells, increasing adhesion molecule expression and releasing inflammatory cytokines such as interleukin-6 (IL-6) and tumor necrosis factor-alpha (TNF-α), which amplify coagulation and inhibit fibrinolysis." (PMID 39857994, 2025). "This normalization interrupts calcium-dependent inflammatory signaling, curbing the production of pro-inflammatory cytokines such as TNF-α and IL-6, thereby further reducing the pro-inflammatory milieu within the tumor microenvironment." (PMID 40243559, 2025). "Activation of IL-6/STAT3, a classic signaling pathway in tumor cells, begins when IL-6 binds to IL-6Rα and gp130 receptor subunits on the membrane surface to form a complex that triggers phosphorylation of JAK kinase and ultimately activation of STAT3." (PMID 41041638, 2025). "For example, pro-inflammatory cytokines in the tumor microenvironment (e.g., IL-6, TNF-α, and IL-1β) can activate signaling pathways (e.g., NF-κB and STAT3) that promote tumor cell proliferation, invasive capacity, and resistance to therapy." (PMID 39940440, 2025). "Once activated, they subsequently also secrete pro-inflammatory cytokines such as TNF-α, IL-1β, IL-6, IL-8, IL-12, and IL-23, which work together to suppress tumor growth." (PMID 40427130, 2025). "The use of Transwell chambers allowed us to isolate the contributions of CAFs and tumor cells to IL-6 secretion, clarifying their respective roles." (PMID 40718440, 2025). "Inflammation-related markers, such as interleukin-6 and C-reactive protein, which are often elevated in frail individuals, are also known to promote tumor progression and metastasis." (PMID 40684433, 2025). "Prior research has demonstrated that IL-6 can stimulate the formation of blood vessels in tumors, facilitate the spread of tumor cells, and hinder the body’s natural defenses against tumors." (PMID 39802656, 2025).
tumor (continued). "In HNSCC tumors, IL-6 (often produced by tumor or stromal cells under chronic inflammation) drives the polarization of tumor-associated macrophages (TAMs) toward an M2, pro-tumoral phenotype." (PMID 41374963, 2025). "Consistent with the THP1 data, PBMCs directly co-cultured with MDA-MB-231 cells showed a robust increase in IL6 secretion (~7-fold) into the supernatant, indicating that tumor-induced immune education occurs in primary human cells." (PMID 41514627, 2025). "Inflammatory CAFs secrete IL-6 and facilitate tumor growth, whereas myofibroblastic CAFs contribute to the formation of the surrounding stroma." (PMID 41155765, 2025). "TAMs secrete a multitude of factors (e.g., EGF, FGF, IL-6) that activate key pro-survival and proliferative signaling pathways in EC tumor cells, such as PI3K/Akt/mTOR and JAK/STAT pathways." (PMID 40746533, 2025). "Specifically, the elevated production of chemokines, metabolites, and growth factors (e.g., IL-6, TGF-β, VEG-F, etc.)by tumor-induced immune cells can cause systemic changes that promote suppression of adaptive immunity." (PMID 40125553, 2025). "IL-6, a key regulator of MDSCs recruitment and activation, exhibits a positive correlation with immunosuppressive cell infiltration in the tumor microenvironment." (PMID 40969768, 2025). "The inhibition of IL-6 signaling slows tumor growth and improves the effectiveness of immunotherapy." (PMID 41179937, 2025). "This formulation enabled tumor-specific delivery, inhibited NF-κB nuclear translocation, reduced IL-6 secretion, and mitigated immunosuppression." (PMID 40936705, 2025). "The dual roles of key cytokines such as TNF-α, TGF-β, IL-6, and IL-10, which act as both tumor suppressors and promoters depending on the tumor context, highlight the complexity of targeting these pathways therapeutically." (PMID 40933989, 2025). "Serum CRP levels are known to correlate with the serum levels of several proinflammatory cytokines, such as interleukin-6 (IL-6), and IL-6 has been reported to induce tumor progression via hyperactivation of the IL-6/JAK/STAT3 pathway." (PMID 40638018, 2025). "Other tumor-derived factor like tumor necrosis factor-α (TNF-α) and interleukin-6 (IL-6) are also involved in MSC tumor-tropism by promoting endothelial adhesion and remodeling the cytoskeletal migration system." (PMID 39971901, 2025). "In cancer, neutrophils release VEGF, IL-6, and MMPs, which promote angiogenesis, tumor growth, and metastasis." (PMID 40370772, 2025). "Pre-exposure to cisplatin induces apoptosis resistance and senescence-associated phenotype in MSCs, while also increasing the secretion of IL-6, IL-8 and other cytokines, thereby enhancing the chemoresistance and stemness of tumor cells." (PMID 40676710, 2025). "The inflammatory factors produced during this process, such as IFN-β, TNF-α, IL-6, and IL-1β, play important roles in immune responses, collectively triggering systemic anti-tumor immunity and inhibiting tumor growth." (PMID 40756351, 2025). "The immunosuppressive role of IL-6 contributes to immune evasion by suppressing anti-tumour immune responses, particularly by promoting regulatory T-cell expansion and inhibiting cytotoxic T-cell activity." (PMID 41561529, 2025). "Treatment with ECH147 downregulated IL-6, suggesting a potential anti-tumor effect by decreasing of IL-6-related pathways involved in CRC metastasis." (PMID 41256010, 2025). "Chemotherapy drugs can further activate NF-κB signaling, inducing IL-6 expression in both tumor and stromal cells." (PMID 40104495, 2025). "IL-6 promotes tumor cell proliferation, survival, and metastasis via the JAK-STAT3 pathway, which upregulates genes involved in cell cycle progression and angiogenesis." (PMID 40563651, 2025). "The IL-6/JAK/STAT3 signaling pathway plays a critical role in regulating the tumor microenvironment, thereby promoting tumor growth, invasion, and metastasis." (PMID 40332515, 2025).
tumor (continued). "IL-6 is a pleiotropic cytokine that promotes inflammation and tumor cell proliferation, enhancing tumor cell migration, invasion, and metastasis." (PMID 40670983, 2025). "Further evidence shows that IL-6 neutralization improves tumor rejection when combined with ICB and simultaneously alleviates ICB-induced immune-related adverse events." (PMID 40238877, 2025). "Receiver Operating Characteristic (ROC) analysis indicated that TNF-α, IL-6 and IL-12 had the strongest ability to discriminate tumour from normal tissue and provided data-driven cut-offs for subsequent analyses." (PMID 41465261, 2025). "In both tumor and adjacent tissue, the sites of highest IL-6 expression were cancer cells and inflammatory cells infiltrating the tumor, but to a lesser extent, expression also appeared in fibroblasts in the lining." (PMID 41007818, 2025). "Genetic loss of STK11 remodels the tumor cytokine milieu, inducing upregulated expression of proinflammatory mediators—including CXCL7, G-CSF, IL-1β, and IL-6—which promotes neutrophil recruitment and suppresses T-effector cell function." (PMID 41254689, 2025). "Tumor-derived IL-6 and TGF-β synergistically reinforce immunosuppression: IL-6 activates STAT3 to upregulate B7-H3 expression, while TGF-β drives Treg differentiation and confers CD8+ T cells with stem-like exhausted epigenetic states." (PMID 40438103, 2025). "IL-6 is classically known as a protumorigenic cytokine that promotes tumor progression and metastasis." (PMID 41375025, 2025). "Chronic inflammation plays a role as adipose tissue secretes pro‐inflammatory cytokines such as TNF‐α and IL‐6, which promote tumor progression and angiogenesis." (PMID 40387523, 2025). "Tumor cells can induce platelet production through the secretion of interleukin-6 (IL-6), thereby further enhancing their invasive and metastatic capabilities." (PMID 40547304, 2025). "CSCs have been shown experimentally to secrete a cocktail of soluble factors (TGF-β, IL-6, IL-8) that attract neutrophils from the circulation and reprogram them to a pro-tumor N2 phenotype." (PMID 40806546, 2025). "Liposarcoma exosomes (LPS) have been shown to stimulate tumor-associated macrophages (TAMs) to release the pro-inflammatory cytokine IL-6, inducing tumor proliferation and metastasis with miR-92a-3p and miR-25-3p." (PMID 40243783, 2025). "MCPIP1 is a key regulator of PC progression, acting as a tumor suppressor by inhibiting the IL6/JAK/STAT3 signaling pathway." (PMID 40874680, 2025). "The treatment results of α-IL-6 reducing PD-1 expression in tumor-infiltrating CD8+ T cells demonstrated the therapeutic potential of α-IL-6." (PMID 40238877, 2025). "TAMs, as infiltrating macrophages within tumor tissue, have been implicated in promoting NED through the activation of downstream IL-6 signaling pathways." (PMID 40746825, 2025). "This signal recruits monocytes, which, in turn, predominantly differentiate into pro-tumor macrophages that promote tumor growth through IL-6 secretion and fibrin deposition." (PMID 40427136, 2025). "In oncology, targeted agents that inhibit tumor-derived osteolytic cytokines (e.g., IL-6 or PTHrP) and emerging anti-sclerostin antibodies (e.g., romosozumab) further contribute to bone protection." (PMID 41295054, 2025). "Tumor-activated neutrophils release proinflammatory factors (IL-6, IL-8, IL-1β, TNF-α), which activate the ERK pathway and epithelial–mesenchymal transition, driving TC cell migration and invasion." (PMID 40136652, 2025). "Our research revealed that TEXs promote tumor metastasis by inducing IL-6 secretion from DCs; they simultaneously activate DCs and induce tumor antigen-specific CD8+ T-cell responses." (PMID 40659888, 2025). "Tub A, a selective HDAC6 antagonist, exhibits low neurotoxicity and multimodal efficiency: it suppresses pro-inflammatory cytokines (TNF-α and IL-6), restores tumor-suppressive primary cilia, and inhibits viral RNA synthesis." (PMID 41135681, 2025).
tumor (continued). "Immunosuppressive cytokines such as TGF-β, IL-10, and IL-6, secreted by cancer cells, CAFs, and TAMs, modulate the immune system, leading to its suppression and promotion of tumor development." (PMID 40362280, 2025). "Expression of STAT3 in tumor cells is known to drive an immunosuppressive microenvironment through secreted mediators such as IL-6 and IL-1031." (PMID 41509421, 2025). "In the HNSCC TME, tumor cell–derived cytokines and chemokines including IL-6, IL-10, and CCL2 can drive polarization of TAMs toward the M2 phenotype." (PMID 40231472, 2025). "This combination therapy has shown considerable efficacy in remodeling the tumor TME by reducing tumor-infiltrating immune cells such as Tregs and MDSCs while decreasing cytokines like IL-6, TGF-β, and TNF-α." (PMID 40281554, 2025). "IL-6 signalling is usually confined to immune cells and the effects on tumour cells is indirect, since epithelial cells typically lack expression of the IL-6 receptor." (PMID 41497628, 2025). "Compared with patients with low levels of both IL-6 and IL-1β, patients with high levels of both IL-6 and IL-1β have significantly shorter overall survival and progression-free survival, a lower tumor control rate, and a reduced high-dose intensity of GEM." (PMID 40948749, 2025). "Through a transglutaminase-2-dependent mechanism, IL-1β increases the aggressiveness of cancer cells in the tumor microenvironment by inducing the production of IL-6." (PMID 40699769, 2025). "Reduction in IL-6 levels translated into decreased tumour activity, indicating the central role of the IL-6/Janus kinase 2 (JAK2)/STAT3 pathway in the mechanism of action of BBR." (PMID 41226384, 2025). "NDs with a higher sp3/sp2 carbon ratio effectively reduce the proangiogenic activity of tumor cells by downregulating key cytokines such as IL-6, IL-8, TIMP-1, TIMP-2, ANG, and ANGPTs." (PMID 40804455, 2025). "The observed increase in IL-6 secretion in co-culture systems underscores the importance of tumor-stroma interactions in driving chemoresistance." (PMID 40718440, 2025). "In macrophages, EGFR activation modulates their polarization (e.g., promoting M2 polarization via PPARγ‐mediated metabolism), cytokine secretion (e.g., HB‐EGF, IL‐6), and infiltration, thereby supporting tumor progression and inflammation." (PMID 40859900, 2025). "Among these, IL-2, IL-6, IL-8, and IL-10 are of particular interest due to their complex roles in tumor-promoting inflammation and immune regulation, making them potential therapeutic targets." (PMID 41226910, 2025). "In a pancreatic cancer mouse model, the genetic ablation of Sin3B, a chromatin scaffold protein essential for senescence induction, resulted in delayed tumor growth, an effect associated with reduced expression of SASP factors, including IL-1 and IL-6." (PMID 40703657, 2025). "Tumor-derived IL-6 activates the STAT3–ERK1/2 signaling cascade in neutrophils, thereby promoting their prolonged survival and functional activation." (PMID 41254689, 2025). "IL-6 demonstrates context-dependent effects, promoting both inflammation and tumor progression through signal transducer and activator of transcription 3 (STAT3) signaling." (PMID 40806379, 2025). "This selective nature is supported by the finding that only HEVs and the tumor vasculature are responsive to the IL-6-induced upregulation of adhesion molecules." (PMID 41375025, 2025). "As for predictive biomarkers of resistance, emerging data highlight factors such as PTEN loss or PI3K pathway activation in tumors (which can exclude T cells) and certain cytokines (elevated IL-6 or IL-8), as markers of an immune-cold tumor." (PMID 41374963, 2025). "Cancer, especially advanced cancer, further amplifies this inflammatory milieu: tumours secrete cytokines (such as IL-1β, IL-6, and TNF-α) as part of immune evasion and tumour progression processes." (PMID 41149069, 2025).
tumor (continued). "In particular, IL-10 plays a key role in modulating inflammation and supporting tumor growth by regulating cytokines such as IL-12/IL-23 and IL-6, which stimulate inflammatory T cells." (PMID 40563468, 2025). "Cytokines, particularly IL-6 and IL-8, serve pivotal roles in prostate carcinogenesis, where tumor-secreted factors remodel the TME to accelerate disease progression." (PMID 41394847, 2025). "Several studies have reported that in addition to IL-6, tumor-derived M-CSF and PGE2 are capable of inducing DC3 development." (PMID 40687784, 2025). "In mouse xenograft models, peritumoral liver tissue exhibits increased microvascular density and elevated expression of proangiogenic genes, including IL-6 and IL-6R, compared to tumor core tissue." (PMID 40918452, 2025). "In CRA, tumor and macrophage-produced inflammatory cytokines, especially IL-6, stimulate the liver to produce hepcidin." (PMID 39926283, 2025). "Phosphorylation of Signal Transducer and Activator of Transcription 3 (STAT3) and activation of Janus kinases (JAKs) are two mechanisms by which interleukin-6 (IL-6) promotes tumour development in cancer." (PMID 41153383, 2025). "The inflammatory microenvironment formed by inflammatory factors such as IL-1β, TNF-α, and IL-6 can promote the proliferation and interstitial transformation of tumor cells, thereby inducing their invasion and metastasis to adjacent or distant tissues." (PMID 40606986, 2025). "This subset highly expresses markers such as IL-6 and RGS5, and promotes tumor progression through mechanisms including the IL-6/IL-6R axis and the exosomal miR-9-5p pathway." (PMID 41445734, 2025). "This suggests that the tumor microenvironment itself can modulate immune responses by dampening IL-6 production in circulating immune cells like PBMCs." (PMID 40484866, 2025). "These recruited TAMs secrete high levels of CCL2 and IL-6, which act on tumor cells via CCR2 and IL-6R, respectively." (PMID 40963633, 2025). "OC is typically classified as a “cold” tumor, often due to IL6-induced immunosuppression through the activation of signaling pathways like STAT3 in cancer cells." (PMID 40427188, 2025). "The IL-6 has been demonstrated to accelerate angiogenesis and inhibit ferroptosis, thus promoting the progression and metastasis of tumours." (PMID 40076898, 2025). "Our OIRRA data showed that tumour samples that express high levels of IL‐11 also up‐regulate IL‐6 expression, potentially triggered by TGFB." (PMID 40673604, 2025). "Concurrently, triggering the release of proinflammatory cytokines such as tumor necrosis factor‐alpha (TNF‐α) and IL‐6, promoting the phagocytosis and subsequent elimination of tumor cells." (PMID 40900811, 2025). "These cells secrete cytokines and chemokines such as IL-1β, IL-6, and IL-8, which trigger inflammation and promote tumor growth." (PMID 41255580, 2025). "IL-6 belongs to the broad class of cytokines that act intrinsically on cells through distinct signaling pathways to sustain tumor growth." (PMID 41376623, 2025). "Exosomal miR-423-3p derived from cervical cancer can also inhibit STAT3 phosphorylation by targeting cyclin-dependent kinase 4, which inhibits M2 polarization of macrophages and reduces IL-6 expression, which in turn inhibits tumor progression." (PMID 40612677, 2025). "In the tumor microenvironment, mast cells release histamine and various cytokines, including IL-4, IL-6, IL-9, IL-10, IL-1β, and TGF-β1." (PMID 39814702, 2025). "A reduction in levels of TNF‐α and IL‐6, cytokines known to drive tumor progression, inflammation, and metastasis formation, was observed." (PMID 40838679, 2025). "The tumor microenvironment in PC is characterized by chronic inflammation with overproduction of cytokines such as IL-6, TNF-α, and IL-1β." (PMID 41514529, 2025). "In the TME, the molecules secreted by tumor cells stabilize Th2 subsets that release IL-6, which act in an autocrine feedback loop to support tumor development." (PMID 41376623, 2025).